STAT3 (signal transducer and activator of transcription 3)
Diseases named in the same sentence as STAT3 in open-access papers (continued):
Sharing a sentence is not in itself a finding about the gene and the disease.
liver cancer (291 papers, 2008 to 2025). An epithelial or non-epithelial malignant neoplasm that arises from the liver. "In this study, we used HLJ1-knockout (Dnajb4–/–) mice and demonstrated that HLJ1 deficiency leads to hepatic gene signatures linked to chemical-induced liver cancer and IL-6/STAT3 signaling." (PMID 39738726, 2024). "Using whole-genome transcriptomic analysis, we demonstrate that HLJ1 deficiency in mice results in altered gene signatures enriched in pathways associated with chemically induced liver cancer and IL-6/STAT3 signaling activation." (PMID 39738726, 2024). "Phosphorylation of STAT3 in liver cancer cells causes it to be transported into the nucleus and promotes the malignant progression of liver cancer." (PMID 37853052, 2023). "The activation of JAK2/STAT3 signaling pathway causes the reduction of the adriamycin-induced aging of cells, and obviously promotes liver cancer cells proliferation." (PMID 37716993, 2023). "The overexpression and ubiquitous activation of STAT3 has been associated with metastasis, immune suppression, and tumor progression in liver cancer." (PMID 37765047, 2023). "A recent study demonstrated that the IL6/STAT3 signaling cascade mainly causes CD133 + enrichment in liver cancer." (PMID 34368140, 2021). "In vitro experiments using liver cancer cells underline that STAT3 regulates cell survival and that inhibition of this molecule blocks the anti-apoptotic activity of IL-6 on these cells." (PMID 32820432, 2021). "The interaction between CIRP and STAT3 has been implicated in liver cancer, in which the tumor-bearing WT mice had a higher level of p-STAT3 than CIRP–/– mice." (PMID 32027619, 2020). "Consistently, the potentiation of cell death induced in liver cancer cell cultures by the combined treatment with taxol and TNFα was associated with reduced levels of both phosphorylated STAT3 and SOCS3, one of the STAT3 target genes." (PMID 31653043, 2019). "In this study, we found that CK-induced ERS in liver cancer cells was associated with reduced p-STAT3." (PMID 29921768, 2018). "HBV-induced primary liver cancer, advanced liver cancer recurrence and metastasis are associated with persistent inflammation accompanying the expression of STAT3." (PMID 32201498, 2018). "High levels of STAT3 are associated with aggressive progression, metastasis, and recurrence of liver cancer." (PMID 29115974, 2017). "In human liver cancer cells, inactivated STAT3 causes the inhibition of IL-6-mediated anti-apoptotic activity." (PMID 27861147, 2017). "Persistent STAT3 activation in liver cancer cells is also associated with invasion, survival, proliferation, and tumorigenesis of liver cancer cells." (PMID 26883202, 2016). "The positive regulation of JAK2/STAT3 signaling pathways has also implicated in CD276-mediated epithelial-to-mesenchymal transition in liver cancer." (PMID 27329595, 2016). "Signal transducer and activator of transcription 3 (STAT3) constitutively expresses in human liver cancer cells and has been implicated in apoptosis resistance and tumorigenesis." (PMID 23533997, 2013). "It was likely that both STAT3 and NF-kB signals were required for IL-6 induced liver cancer progression, though the specific underlying mechanism remains unclear." (PMID 34657635, 2021). "Therefore, there is a certain association between FN1 and STAT3 in liver cancer." (PMID 40772037, 2025). "Interestingly, the STAT3 Tyrosine 640 into Phenylalanine (Y640F) hotspot gain-of-function mutation reported in various lymphoid malignancies has also been detected in patients with liver cancer." (PMID 31557897, 2019). "STAT3 was found to be downregulated in liver cancer patients, which contradicts the majority of current research." (PMID 40772037, 2025). "In liver cancer, it induces autophagy, while in CRC, the histone deacetylase inhibitor trichostatin A (TSA) reduces JAK2/STAT3 signaling, causing AK2/STAT3, leading to damage in 16HBE cells and contributing to asthma development." (PMID 40165005, 2025).
liver cancer (continued). "In liver cancer cells, growth factors and cytokines can activate STAT3, which contains LLPS-prone domains, including the N-terminal domain (NTD), coiled-coil domain (CCD), and SRC homology 2 (SH2) domain." (PMID 41280670, 2025). "For example, exosomal circZFR derived from CAFs can inhibit the STAT3/NF-kappa B pathway in liver cancer cells, promoting cisplatin resistance." (PMID 40852592, 2025). "The tumor hepatocytes expressed high levels of ALB, AFP, and STAT3, with the later two genes known to be altered in liver cancer and fibrosis, respectively." (PMID 40766612, 2025). "Pericarcinomatous tissue of patients with liver cancer was collected as fibrosis replacements to identify the pathological STAT3 activation at different stages of liver fibrosis." (PMID 41163803, 2025). "The deubiquitinase USP9x has been previously studied in several types of cancer including its involvement in the promotion of liver cancer through modulation of JAK2/STAT3 signaling." (PMID 39075050, 2024). "Research has found that Brusatol inhibits the progression of liver cancer by weakening STAT3-driven metastasis in liver cancer cells through altering the levels of epithelial–mesenchymal transition related proteins." (PMID 38974037, 2024). "Nonetheless, the combined targeting of NF-κB and STAT3 offers a promising approach for the management of liver cancer such as HCC, necessitating further compelling experiments to confirm the robustness of vinpocetine’s effects." (PMID 39480853, 2024). "Further, the CucD-mediated downregulation of genes and proteins belonging to the PI3K/AKT/mTOR, MAPK, and JAK2/STAT3 cascades has been highlighted in liver cancer." (PMID 39770403, 2024). "The examination of pathological tissue samples obtained from liver cancer patients revealed a correlation between higher STAT3 activity levels and larger tumor volume, poorer prognosis, and increased postoperative recurrence rate." (PMID 38183094, 2024). "The deletion of SOCS3 leads to STAT3 pathway activation, promoting cell proliferation and increasing the incidence of hepatitis-induced liver cancer." (PMID 38920657, 2024). "Third,we characterized the selective killing profile of this small-moleculeSTAT3 inhibitor by testing the anticancer activities of STAT3-negativePC3 cells and a variety of STAT3-dependent tumor cells, includingPDAC cells, and liver cancer cells." (PMID 38559310, 2024). "This augmentation promotes the stabilization of the binding between MUC1 and p-STAT3, triggering the activation of the JAK1/STAT3 signaling cascade, thereby participating in the progression of liver cancer." (PMID 38256141, 2024). "This study aimed to evaluate the effect of four selected active chalcone thio-derivatives on the NF-κB and STAT3 signaling pathways involved in inflammatory processes and cell proliferation in human liver cancer cells." (PMID 39409068, 2024). "Inhibiting STAT3 activity reversed the effect of knocking down PKM2 on cell migration, suggesting that PKM2-induced liver cancer cell migration is mediated by STAT3." (PMID 37861491, 2023). "It was demonstrated in hepatic stellate cells that the conditioned media from liver cancer cells enhance the FAP expression in them in a STAT3-dependent manner." (PMID 36825204, 2023). "Cryptotanshinone induced liver cancer cells apoptosis and enhanced the effect of Arsenic trioxide by downregulating phosphorylated STAT3, Bcl-2 in vitro and in vivo." (PMID 36865794, 2023). "Another study revealed that PTPRO suppress tumor cell proliferation and promotes apoptosis by dephosphorylating signal transducer and activator of transcription 3 (STAT3) in liver cancer." (PMID 36816740, 2023). "As expected, STAT3 depletion blunted the rate of EdU-labeled cells; whereas STAT3 upregulation enhanced the rate of EdU-labeled cells, indicating that STAT3 can promote the proliferative activity of liver cancer cells." (PMID 36656267, 2023).
liver cancer (continued). "In studies of liver cancer metastasis, STAT3 was founded to be cooperated with Snail-Smad3/TGF-B1 signaling pathway, promoting cell migration." (PMID 37038114, 2023). "Chrysin significantly inhibited the overexpression of PD-L1 and increased the proportion of CD4/CD8-positive T cells by blocking the JAK/STAT3 and NF-κB pathways, inhibiting the growth of liver cancer cells both in vivo and in vitro." (PMID 38155974, 2023). "On the other hand, inhibiting STAT3 activity can result in the downregulation of survivin gene expression, facilitating the induction of apoptosis in liver cancer cells." (PMID 37892997, 2023). "The participation of STAT3 in oncogenesis, angiogenesis, anti-apoptosis, and drug resistance has attracted the attention of researchers as a therapeutic target in liver cancer." (PMID 37765047, 2023). "In liver cancer cells, IL-37 inhibited IL-6 expression by hindering the STAT3 pathway, thereby inhibiting the inflammatory response of IL-6." (PMID 35741608, 2022). "Studies indicated that STAT3 was highly expressed in several tumor tissues and cell types, and also showed the same characteristics in liver cancer cells." (PMID 36267958, 2022). "Interleukin-6 (IL-6) has been confirmed to participate in the occurrence of HBV-related liver cancer by activating the STAT3 pathway." (PMID 35359408, 2022). "Based on accumulating evidence, constitutive activation of NF-κB and STAT3 occurs in various cancer types, such as colon, gastric, lung, and liver cancers." (PMID 35890318, 2022). "As we found that IL-6 induces STAT1 transcriptional activity upon STAT3 depletion, we next sought to analyze the expression of STAT1 and STAT3 regarding infiltrating immune cells in human liver cancer tissues." (PMID 35267462, 2022). "Previous studies have also reported that HCC is an inflammation-related cancer and that IL-6-dependent STAT3 activation is a critical instigator of inflammation-induced liver cancer." (PMID 35862398, 2022). "Cellular-JUN and signal transducer and activator of transcription 3 (STAT3) are critical regulators of liver cancer development and progression." (PMID 34954190, 2022). "The levels of IL-6, phosphorylated JAK2 and phosphorylated STAT3 were significantly increased in liver cancer cells." (PMID 36591515, 2022). "variant Indonesia and Philippines against the expression of IL-6 and STAT3 was examined in liver cancer cell line." (PMID 37829248, 2022). "IL-6, phosphorylated JAK2 and phosphorylated STAT3 protein levels were significantly increased in liver cancer cells." (PMID 36591515, 2022). "Saffron can inhibit the activation of STAT3 pathway and non-receptor protein tyrosine kinase by inhibiting the DNA binding activity of STAT3 in IL-6 stimulated liver cancer cells." (PMID 36591515, 2022). "Kahweol, a diterpene in coffee, induces apoptosis in liver cancer cells acting through the Src/mTOR/STAT3 signaling pathway." (PMID 36428575, 2022). "A lncRNA down-regulated in liver cancer stem cells (lncDILC) has been shown to interfere with NF-κB-mediated IL-6 expression via inhibiting STAT3 signaling, and thus has prognostic value for patients with HCC." (PMID 35141283, 2022). "The abnormally over-expressed and activated signal transducer and activator of transcription 3 (STAT3) signaling pathway have also been proved to be impaired by ALT in liver cancer cells." (PMID 34899346, 2021). "This STAT3 expression is negatively correlated with HNF4α, and stress-induced activation of the STAT3–HNF4α inflammatory loop leads to the decreased expression of miR-122, which is responsible for liver cancer cell migration and invasion." (PMID 34771521, 2021). "Studies have shown that it is closely related to liver fibrosis and the occurrence of liver cancer, especially STAT3." (PMID 34483930, 2021). "Crocin displayed an anti-liver cancer potential through the inhibition of the IL-6/STAT3 signaling pathways." (PMID 34639131, 2021).
liver cancer (continued). "And scutellarin was found to reduce the expression of apoptotic factor Stat3 in liver cancer cells, and inhibit the metastasis of liver cancer cells by inhibiting the STAT3/Girdin/Akt signaling pathway." (PMID 34539390, 2021). "Many studies have proved that STAT3 as a nuclear transcription factor promoting tumor development plays an important role in the proliferation of liver cancer, and inhibition of STAT3 activity can inhibit the proliferation of HCC cells." (PMID 34858832, 2021). "In mechanism, we found that activation of AhR contributed to the upregulation of IL-6, which further promotes liver cancer development through a STAT3 and NF-kB/TIM4 dependent manner." (PMID 34657635, 2021). "Further analyses found that TPTEP1 inhibits IL-6-induced phosphorylation of STAT3, thereby inhibiting the transcriptional activity of STAT3 and increasing the sensitivity of liver cancer cells to cisplatin." (PMID 33390845, 2021). "Curcumol inhibited the expression of PD-L1 by overlapping the HIF-1α and p-STAT3 (T705) signaling pathways in liver cancer." (PMID 34884892, 2021). "RPN2 promotes liver cancer metastasis and reduces autophagy by regulating STAT3 and NF-κB signaling pathways." (PMID 33613755, 2021). "The enhancement of Nanog expression promoted epithelial–mesenchymal transition (EMT) through activation of the Stat3/Snail signaling system in liver cancer cells." (PMID 33665763, 2021). "In this study, we identified a novel mechanism in which TDO2, through Trp/Kyn metabolism, activated AhR/IL-6/STAT3/NF-kB signaling and promoted liver cancer progression." (PMID 34657635, 2021). "It has been reported AD activates PI3K/Akt1 and STAT3 in certain types of cells, such as the epithelial cells, the endothelial cells, and the liver cancer cells." (PMID 33815378, 2021). "Overexpression of MMP-9 and MMP-2 is associated with postoperative tumors in patients with liver cancer and accelerates the invasion and migration capacity of HCC cells by regulating the JAK/STAT3 signaling pathway." (PMID 34976809, 2021). "Mammalian target of rapamycin–signal transducer and activator of transcription 3 (mTOR–STAT3) can inhibit liver cancer cell glycolysis by inhibiting hexokinase 2 (HK2)." (PMID 33607990, 2021). "A prominent example of such a regulatory interaction is found between lncRNA-ATB and IL11 mRNA leading to the stabilization of the latter which results in an activated IL11/STAT3 signalling and enhanced metastatic potential of liver cancer cells." (PMID 32727085, 2020). "For instance, the JAK2/STAT3 axis is a crucial driver of liver-associated MDSCs and inhibition of STAT3 increased the efficacy of CAR-T cells in liver cancer metastasis." (PMID 32972405, 2020). "For example, STAT3-induced lncRNA HOXD-AS1 facilitates liver cancer metastasis by competitively sponging miR-130a-3p and regulating SOX4." (PMID 32351327, 2020). "Several studies have demonstrated that CDK5 activity modulates the signal transducer and activator of transcription 3 (STAT3) protein through Ser-727 phosphorylation in neurons, head and neck squamous cell carcinoma, and liver cancer cells." (PMID 31395805, 2019). "The expression of STAT3 can be reduced by mTOR blocking, which is closely related to the invasion and metastasis of liver cancer cells." (PMID 31696055, 2019). "To verify that the tumor suppressive roles of miR‐125b‐5p in liver cancer were achieved via inhibiting STAT3, we introduced a STAT3 eukaryotic expression plasmid into HCCLM3 and HUH7 cells to induce WT‐STAT3‐3′UTR independent ectopic STAT3 expression." (PMID 31065520, 2019). "Among the top upregulated genes, Nogo-B attracted our attention because it was previously reported to regulate liver cancer proliferation through the IL-6/STAT3 pathway." (PMID 31358770, 2019). "In conclusion, our data suggest that SSd controls liver cancer proliferation through suppression of the p-STAT3/C/EBPβ signaling pathway inhibiting COX2 expression." (PMID 31191326, 2019).
liver cancer (continued). "Consistently, HDAC3 knockdown in human liver cancer cells HepG2 using siRNA significantly increased ac-STAT3 expression level and remarkably inhibited cell growth." (PMID 29540666, 2018). "Application of the JAK2 inhibitor AZD1480 and IL6 neutralizing antibody showed the CD90 and SHH/Gli‐regulated liver cancer stem cell functions were mediated by the IL6/JAK2/STAT3 pathway." (PMID 29722127, 2018). "For more information about the downstream pathways associated with CD90‐mediated stem cell functioning in liver cancer cells, the IL6/JAK2 signalling components and STAT3 phosphorylation were further analysed in liver cancer cells 97L and Huh7." (PMID 29722127, 2018). "Taken together, these results showed that the proliferation, sphere formation and migration capacities of CD90+ liver cancer cells involved activation of IL6/JAK2/STAT3 signalling through the SHH/Gli pathway." (PMID 29722127, 2018). "In this study, we determined that HDAC3 promotes liver regeneration and liver cancer cells proliferation through the signal transducer and activator of transcription 3 (STAT3) signaling pathway." (PMID 29540666, 2018). "We also further verified that IL6/JAK2/STAT3 signalling functions downstream of the SHH/Gli pathway in liver cancer stem cells." (PMID 29722127, 2018). "A recent study has shown that forced expression of ISG20 promotes metastases and angiogenesis via the IL-8/p-JAK2/p-STAT3 signalling pathway, both in liver cancer cell lines and in animal models, suggesting a pro-tumour role of ISG20." (PMID 29963243, 2018). "The inhibitory effect on STAT3 phosphorylation and activity as well as cell viability, migration, and colony forming ability by Raloxifene was examined in human liver cancer cells." (PMID 28430601, 2017). "Following this activation step, STAT3 homodimers are formed and translocated to the nucleus leading to the activation of many downstream target genes related to liver cancer development." (PMID 28970500, 2017). "Raloxifene inhibited the targets of STAT3, such as Bcl-2, Bcl-xl and survivin and cell viability, cell migration, and colony formation in liver cancer cells." (PMID 28430601, 2017). "All of these results indicate that phosphorylated-STAT3 played a key role in ATO combined with CT–induced liver cancer cell apoptosis." (PMID 28187727, 2017). "Raloxifene inhibited STAT3 phosphorylation and resulted in the induction apoptosis on human liver cancer cell-lines." (PMID 28430601, 2017). "As IL-6/GP130/STAT3 signaling is essential for cell viability and colony formation in liver cancer cells, we examined cell viability by MTT assay." (PMID 28430601, 2017). "We also examined the expression of STAT3 target genes, such as Bcl-2, Bcl-xl, and survivin in liver cancer cells by western blot." (PMID 28430601, 2017). "Constitutive activation of Signal Transducer and Activator of Transcription 3 (STAT3) induced by IL-6 is frequently detected in liver cancer and has emerged as a viable molecular target for liver cancer treatment." (PMID 28430601, 2017). "Aberrant activation of STAT3 has been demonstrated to maintain the CSC population of liver cancer through increased expression of NANOG." (PMID 28617312, 2017). "The reason we chose Hep-3B for this study is that the phosphorylation level of STAT3 in Hep-3B liver cancer cells is low." (PMID 28430601, 2017). "Our study provides strong evidence of the anti-tumor growth potency of ATO combined with CT and that phosphorylated-STAT3 played a key role in ATO combined with CT–induced liver cancer cell apoptosis." (PMID 28187727, 2017). "One of the most important downstream target genes of IL-6 is STAT3, which is constitutively activated in various types of cancer, including liver cancer." (PMID 28430601, 2017). "Hepatitis B virus promotes the migration of liver cancer cells by downregulating miR-340-5p expression to induce STAT3 overexpression." (PMID 28413603, 2017).